SMAD3 (SMAD family member 3)
Diseases named in the same sentence as SMAD3 in open-access papers (continued):
Sharing a sentence is not in itself a finding about the gene and the disease.
renal fibrosis (continued). "Blockade of TGF-β/Smad3-mediated renal fibrosis by downregulating TGF-β1 and microRNA-21 expression, thereby restoring the balance of Smad signaling by upregulating an inhibitory Smad7, resulting in a possible underlying mechanism by which CHYS inhibits diabetic nephropathy associated with fibrosis." (PMID 24646636, 2014). "Transforming growth factor‐β/Smad3 signaling plays a critical role in promoting renal fibrosis." (PMID 24973329, 2014). "Once Smad7 is degraded, activation of Smad3 and renal fibrosis is enhanced." (PMID 24646636, 2014). "Taken together, the present study revealed that enhanced Sp1-TGF-β1/Smad3-NF-κB signaling and loss of miR-29 may be mechanisms by which deletion of Smad7 promotes ANG II-mediated renal fibrosis and inflammation." (PMID 23301086, 2013). "This study analyzes the hypothesis that blockade of Smad3 attenuates the development of TGF‐β1‐driven renal fibrosis." (PMID 24744860, 2013). "Enhanced Sp1-TGF-β1/Smad3-NF-κB signaling may be the major mechanistic pathway by which deletion of Smad7 promotes ANG II-mediated renal fibrosis and inflammation." (PMID 23301086, 2013). "Moreover, genetic ablation of SMAD3 in murine models significantly attenuates renal fibrosis." (PMID 41323737, 2025). "Importantly, we also found that GPX4 was a downstream target gene of Smad3 and functioned to protect against Smad3-mediated renal fibrosis as silencing GPX4 restored UUO-induced severe renal fibrosis in Smad3 KO mice and in TGF-β1-stimulated Smad3 KO MEFs and SIS3-treated HK-2 cells." (PMID 41079940, 2025). "Thus, it is possible that targeting the Smad3/GPX4-ferroptosis regulatory pathway may be a promising therapeutic strategy for treatment of renal fibrosis." (PMID 41079940, 2025). "Xiaoping Yang and colleagues found that bile acid receptor agonists could reverse TGF-β1-induced renal fibrosis by regulating the Farnesoid X receptor, p-SMAD3, and TAZ in iPSC-derived renal organoids, demonstrating that bile acid receptor agonism exists in the early stage of renal fibrosis." (PMID 40926989, 2025). "Thus, in CKD patients and mice, Smad3 activation is associated with decreased GPX4 expression, which may contribute to ferroptosis and progressive renal fibrosis." (PMID 41079940, 2025). "Thus, (−)-epigallocatechin gallate may ameliorate renal fibrosis by targeting Notch through the inhibition of the TGFβ/Smad3 pathway in diabetic mice." (PMID 41020857, 2025). "Importantly, deficiency of SMAD2 and SMAD3 improved the renal fibrosis in UUO mice, and there is no obviously difference in renal fibrosis between WT and Sirt2tKO mice when SMAD2 and SMAD3 is deficient." (PMID 37777567, 2023). "Thus, Smad3 plays a critical role in the development of renal fibrosis in many kidney diseases." (PMID 35541902, 2022). "Therapy targeting Smad3 may be a specific and effective treatment for renal fibrosis." (PMID 35502169, 2022). "Whether JPYSF plays a role in alleviating renal fibrosis via targeting miR-192-5p to inhibit the activation of TGF-β/Smad3 signaling and JPYSF keeps renal handling of fluid balance by targeting miR-192-5p to modulate Na+/K + -ATPase through in CKD warrants further exploration." (PMID 36105201, 2022). "This may also explain why deletion of Smad3 inhibits UUO-induced renal fibrosis in CRP Tg mice." (PMID 34671208, 2021). "Collectively, the TGF-β/Smad3-mediated lncRNAs may act as anti-fibrotic or pro-fibrotic mediators in the fibrotic process by binding to Smad3, Smad7, or inflammatory molecules to inhibit or enhance renal fibrosis and inflammation." (PMID 34054586, 2021). "Moreover, the inhibition of Smad3 protein and related regulatory factors of extracellular matrix could contribute to alleviation of renal fibrosis." (PMID 34035828, 2021).
renal fibrosis (continued). "Interestingly, a recent study also revealed that decreased human lnc-TSI (TGF-β/Smad3-interacting long non-coding RNA) correlates with the degree of renal fibrosis in patients with IgA nephropathy and treatment with lnc-TSI inhibits renal fibrosis by blocking its binding to the MH2 domain of Smad3." (PMID 32258028, 2020). "Therefore, treatments by rebalancing Smad3/Smad7 signaling or by specifically targeting Smad3-dependent non-coding RNAs that regulate renal fibrosis or inflammation could be a better therapeutic approach." (PMID 32258028, 2020). "The differential effects of Arid2-IR in renal fibrosis and inflammation suggest that Arid2-IR may be a downstream mediator of Smad3 in renal inflammation because mice null for Smad3 are protected against Smad3-mediated fibrosis and NF-κB-driven inflammation in a number of renal diseases." (PMID 32295041, 2020). "In addition, CdCl2 can induce renal fibrosis by endorsing TGF-β1/SMAD3/α-SMA/collagen signaling." (PMID 31022990, 2019). "Thus, rebalancing the TGF-β/Smad signaling by downregulating Smad3 and upregulating Smad7 might be an effective strategy for treatment of renal fibrosis." (PMID 30271345, 2018). "In addition, overexpression of latent TGFβ1 was shown to decrease both SMAD2/3 activation (transcription factors of canonical TGFβ1 signaling) and the number of myofibroblasts, which is in line with findings that SMAD3 knockout mice are protected from renal fibrosis." (PMID 29651290, 2018). "Additionally, in patients with chronic kidney disease, SIRT1 activation could protect against renal fibrosis by inhibiting the TGF-β/Smad3 pathway." (PMID 30123131, 2018). "Moreover, FXR suppressed renal fibrosis via downregulating Smad3 in vitro and in vivo." (PMID 27853248, 2016). "Thus, activation of CD32b-Smad3-mTOR signaling may be a key mechanism by which CRP mediates renal fibrosis." (PMID 27221338, 2016). "Whilst this has been shown to be Smad3-dependent in, e.g. renal fibrosis, and our data agree with an effect on the promoter, it may be that processing from pre-miRNA to mature miRNA is the major determinant in their final expression controlled by TGFβ, rather than transcription." (PMID 26687115, 2016). "Thus, phosphorylated Smad3 is the effector of TGF-β-mediated renal fibrosis." (PMID 28100935, 2016). "Indeed, loss of renal Smad7 was found in the kidney with chronic AAN, which may account for TGF-β/Smad3-mediated renal fibrosis." (PMID 25883225, 2015). "Thus, blockade of TGF-β/Smad3-mediated renal fibrosis could be a mechanism by which Smad7 protects against chronic AAN." (PMID 25883225, 2015). "Further studies revealed that inhibition of renal fibrosis in CHYS-treated diabetic rats was associated with inhibition of TGF-β1/Smad3 signaling as demonstrated by upregulation of Smad7 but downregulation of TGF-β1, TGF-β receptors, activation of Smad3, and expression of miRNA-21." (PMID 24646636, 2014). "Furthermore, the renal and glomerular hypertrophy, glomerular accumulation of mesangial matrix and type IV collagen and activation of renal TGF-β1/Smad3 signaling, a key mediator of renal fibrosis, were exacerbated in the diabetic VASH1+/− mice compared with the diabetic wild-type littermates." (PMID 25255225, 2014). "Thus, blockade of TGF-β/Smad3-mediated renal fibrosis could be an important mechanism by which CHYS attenuated diabetic kidney disease." (PMID 24646636, 2014). "In order to explore whether GS-HCl influenced TGF-β signaling in the obstructed kidney, we next analyzed the phosphorylation level of Smad3 proteins, which played a major role in renal fibrosis in the downstream of TGF-β signaling in an in vivo model of obstructive nephropathy." (PMID 24072041, 2013). "Thus, ANG II-induced up-regulation of Sp1 expression and activation of Smad3 may cooperate in the development of ANG II-induced renal fibrosis as seen in WT mice." (PMID 23301086, 2013).
renal fibrosis (continued). "This was further confirmed by pharmacological inhibition in a mouse model of UUO in which blockade of NLRP3 inhibited TGF-β/Smad3 signaling, MMT, and progressive renal fibrosis." (PMID 42157945, 2026). "In renal fibrosis, the TGF-β1/Smad3 signaling pathway is inhibited by PROTAC, which creates a PROTACS that links the E3 ligases VHL and Smad3." (PMID 40225869, 2025). "By using several experimental models (including mouse BMDMs, mouse CAR models, and human renal biopsy samples), this study demonstrates that METTL3 enhances Smad3 levels to facilitate M2‐driven MMT and renal fibrosis in CAR." (PMID 39869489, 2025). "Functional validation experiments demonstrated that silencing METTL3 using siRNA, genetic knockout, or treatment with the inhibitor STM2457 significantly reduced Smad3 expression, disrupted M2‐driven MMT, and alleviated renal fibrosis during CAR." (PMID 39869489, 2025). "The deletion of Smad4 suppressed the binding of Smad3 to the COL1A2 promoter, thus inhibiting the fibrotic response and renal fibrosis." (PMID 40141345, 2025). "Multiple lines of evidence have shown that vitamin D and analogues decrease renal fibrosis progression via the vitamin D receptor and inhibit TGF-β1/Smad3 signaling pathway." (PMID 39787157, 2025). "TGF-β is a key regulator in renal fibrosis and mediates T2DN through its downstream Smad3-dependent mechanisms." (PMID 40969268, 2025). "We observed that artesunate significantly reduced SMAD3 phosphorylation in HKF cells, disrupting the TGF-β/SMAD pathway and potentially mitigating renal fibrosis." (PMID 41323737, 2025). "Urinary exosomal miR-21, miR-29c, and miR-150 promote the M2-MMT process and thereby renal fibrosis by targeting SP1 and the Smad3/TGFβ signaling pathway." (PMID 40332144, 2025). "Our research underscores the critical role of METTL3 in modulating TNF‐β/Smad3 signaling and its downstream effects on MMT and the development of renal fibrosis in CAR." (PMID 39869489, 2025). "This was demonstrated by the findings that silencing GPX4 restored high levels of 4-HNE, TFR1 and the severity of renal fibrosis in the UUO kidney of Smad3 KO mice and TGF-β1-treated Smad3 KO MEFs and HK-2 cells treated with SIS3." (PMID 41079940, 2025). "Animals with renal fibrosis showed decreased SOD activity and increased expression of TGF-β1, TNF, VEGF, Smad3, and Smad7, which correlated with increased expression of miR-148a-3p." (PMID 40004454, 2025). "The findings suggest that ECF and EC can reduce the expression of TGF-β1, Smad3, and α-SMA and attenuate the adenine-induced renal fibrosis." (PMID 40430564, 2025). "In DKD, the expression of miR-30a is typically reduced, contributing to the activation of the TGF-β/Smad3 pathway, which promotes ECM deposition and leads to renal fibrosis." (PMID 40724919, 2025). "Aberrant activation of key molecular pathways, notably TGF-β/Smad3, induces renal tubular epithelial-mesenchymal transition (EMT) and extracellular matrix deposition, thereby accelerating renal fibrosis." (PMID 41487503, 2025). "In vivo, pirfenidone treatment in Pkd1RC/RC mice reduced renal fibrosis, collagen deposition, myofibroblast accumulation, pro-fibrotic gene expression and decreased TGF-β/SMAD3 and mTOR signaling." (PMID 40909512, 2025). "SIRT1 induces deacetylation and deactivation of SMAD3 and SMAD4, thereby inhibiting the profibrotic response of TGF- β1 in vitro and in vivo models of renal fibrosis." (PMID 40514411, 2025). "Anti-TGF-β treatments and Smad3 inhibitor, SIS3, inhibit renal fibrosis in STZ-induced diabetic nephropathy in Tie2-cre;Loxp-EGFP mice." (PMID 40141345, 2025). "Kidney: the IAA novel analogue, MA-35, inhibits the phosphorylation of Smad3, thus reducing TGF-β1 signaling and related renal fibrosis." (PMID 38675450, 2024).
renal fibrosis (continued). "In our study, OA treatment remarkably mitigated renal fibrosis and conserved kidney function by activating Sirt1 and suppressing the TGF-β/Smad3 pathway." (PMID 39687299, 2024). "In preclinical studies, I-BET151 has been shown to inhibit the activation of the TGF-β/Smad3, STAT3, ERK1/2, and NF-kB signaling pathways in renal fibrosis and to reverse renal EMT." (PMID 39215370, 2024). "Formononetin can suppress the Smad3/activating transcription factor 3/SLC7A11 signaling pathway, thereby ameliorating renal fibrosis induced by UUO and FA." (PMID 39769044, 2024). "Collectively, these results indicated that OA repressed renal fibrosis by activating the expression of Sirt1 and blocking the TGF-β/Smad3 pathway." (PMID 39687299, 2024). "In in vitro results, OA treatment markedly inhibited the activation of Smad3 in UUO mice, thereby ameliorating renal fibrosis." (PMID 39687299, 2024). "Following the in vitro results, OA treatment markedly inhibited the activation of Smad3 in UUO mice, thereby ameliorating renal fibrosis." (PMID 39687299, 2024). "The major findings of this study showed that OA ameliorates renal fibrosis by activating the expression and activity of Sirt1 and inhibiting the TGF-β/Smad3 signaling pathway." (PMID 39687299, 2024). "Additionally, quercetin, as an inhibitor of Smad3 phosphorylation, may inhibit renal interstitial fibrosis in UUO mice by inhibiting Smad3-mediated ferroptosis, further confirming the close relationship between ferroptosis and renal fibrosis induced by renal hydronephrosis." (PMID 39021564, 2024). "TGF-β1 induces P2Y12 via a Smad3-dependent mechanism, thereby promoting MMT-mediated renal fibrosis." (PMID 39445007, 2024). "Our investigations have revealed that SIRT2 suppresses renal fibrosis by inhibiting pro-fibrotic TGF-β signaling through the promotion of deacetylation of SMAD2 and SMAD3." (PMID 37777567, 2023). "Based on these studies, PRMT is a key regulator in the TGF‐β1/Smad3 signaling pathway and STAT3 signaling and functions in renal fibrosis." (PMID 37525933, 2023). "Histone methyltransferase (SET9) upregulates SMAD3 and induces high SMA expression in renal fibrosis." (PMID 37762322, 2023). "SMAD4 knockout gene evidenced attenuated renal fibrosis in UUO, apparently through SMAD3 inhibition." (PMID 37762322, 2023). "Our data are in line with other research that identified CHR-mediated inhibition of pro-fibrotic pathways in rat myocardial injury, renal fibrosis and osteoarthritis, by reducing TGF-β1/Smad3, p38, Erk1/2, MMP2 and PERK/TXNIP/NLRP3 signalling." (PMID 38169923, 2023). "VEGFA, as a growth factor essential for angiogenesis, inhibits the expression of Smad3 and miR192, thereby suppressing IGF-β-induced endothelial interstitial transformation and ameliorating renal fibrosis." (PMID 37404805, 2023). "SIRT1 reverses Smad3 acetylation and thereby inhibiting the profibrotic response of TGF-β1 in vitro and in vivo such as in unilateral-ureteric obstruction mouse model of renal fibrosis." (PMID 35795148, 2022). "In UUO-induced renal fibrosis mice model, the HDAC8 inhibitor, PCI34051, inhibited Smad3, STAT3, β-catenin and Snail expressions and activated BMP7 and Klotho renal protective protein expressions." (PMID 35250597, 2022). "It was found that Chrysophanol alleviated renal fibrosis in UUO mice by modulating the TGF-β/Smad signaling pathway, especially inhibiting phosphorylation of Smad3." (PMID 35978370, 2022). "Our previous studies demonstrated a combination of Traditional Chinese Medicine derived Smad7 agonist Asiatic Acid (AA) and Smad3 inhibitor Naringenin (NG), AANG, effectively suppressed the progression of renal fibrosis in vivo." (PMID 36147472, 2022). "It is also reported that the methyltransferase SET9 (also known as SETD7) can interact with the Smad3 N-terminal MH1 domain to increase Smad3 activity and upregulate α-SMA expression during renal fibrosis." (PMID 35541902, 2022).
renal fibrosis (continued). "In the process of renal fibrosis in an animal model with DKD, the increased level of TGF-β interacts with its receptors and triggers activation of Smad-dependent pathways, Smad2 and Smad3 presented higher expression in kidney tissues, and Smad7 was inhibited." (PMID 36601125, 2022). "Since CDDP and DFO interventions did not affect apoptosis, these findings suggest that ferroptosis is a potential target for treatments aimed at delaying renal fibrosis progression, and that the TGF-β1/Smad3 signaling pathway is important in this context." (PMID 35318301, 2022). "In UUO-induced renal fibrosis model, TGF-β1 induces G9a expression via Smad3 activation, and BIX01294 inhibits G9a-mediated H3K9me1 and attenuates renal fibrosis and retains klotho expression." (PMID 35559246, 2022). "This had a functional effect, as mice transplanted with Smad3−/− bone marrow showed a remarkable reduction of collagen I deposition and α-SMA, indicating reduced renal fibrosis in the UUO kidney." (PMID 35990655, 2022). "The rescue experiments confirmed that LSD1 induced renal fibrosis via decreasing SIRT3 expression and activating TGF-β1/Smad3 pathway." (PMID 34983623, 2022). "Renal fibrosis is a common feature of all types of chronic kidney disease (CKD) and is tightly regulated by the TGF-β/Smad3 pathway." (PMID 36091385, 2022). "The microRNAs miR-21, miR-192, and miR-29, which are engaged in renal fibrosis, are regulated by TGF-/Smad3, which also has a role in the pathogenesis of fibrosis in renal tissues." (PMID 36648873, 2022). "In an animal model involving Ang II-induced renal fibrosis, Smad7 knockout mice exhibit elevated TGF-β/Smad3 signaling, more severe renal injury and increased progressive fibrosis compared to the wild-type." (PMID 35237156, 2022). "BSHM reduced both TGF-β1 and Smad3 expression, suggesting that BSHM brought greatly alleviated renal fibrosis and protected against the progression of hypertensive renal damage." (PMID 35502169, 2022). "Researchers determined that POU Class 4 Homeobox 1 (Pou4f1), a direct Smad3 target gene in the TGF-β1-induced MMT process in BMDMs, was a potential therapeutic target to prevent renal fibrosis." (PMID 35990655, 2022). "Overexpression of LSD1 induces renal fibrosis via decreasing SIRT3 expression and activating TGF-β1/Smad3 pathway." (PMID 34983623, 2022). "Reportedly, sorafenib, an xCT inhibitor, can inhibit the TGF-β/Smad3-induced EMT signaling and suppress the CXCR3/CXCL11-mediated macrophage infiltration, ameliorating renal fibrosis." (PMID 35655759, 2022). "It has also been found in renal fibrosis research studies that raised SIRT1 expression can curb TGF-β1 and Smad3 expression to downsize the occurrence of EMT." (PMID 35958178, 2022). "Refer to this strategy, we designed and constructed a novel Smad3-targeting, VHL-recruting PROTAC and confirmed its effects on anti-renal fibrosis and renal function-improving." (PMID 36536448, 2022). "We also evaluated changes in the expressions of Smad2, Smad3, and TGF-β1, which are considered valuable signaling molecules in the progression of renal fibrosis." (PMID 35646947, 2022). "Another study with rat epithelial cells demonstrated that resveratrol stimulated SIRT1 to deacetylate SMAD3, which reversed the TGF-β1-induced upregulation of type IV collagen and fibronectin mRNA levels to attenuate renal fibrosis." (PMID 35277012, 2022). "Judging from some studies regarding renal fibrosis, it has been found that activation of SIRT1 can curb TGF-β1/Smad3 expression to alleviate fibrosis." (PMID 35958178, 2022). "Several reports have shown that transforming growth factor-β (TGF-β)/Smad3 signaling pathways contribute to EMT and renal fibrosis, with most having focused on the role of Smad3 phosphorylation in the EMT process in DN." (PMID 34122724, 2021).